IGHV8-51-1 (immunoglobulin heavy variable IGHV8-51-1 (non-functional))
Description:
Probable non-functional open reading frame (ORF) of V region of the variable domain of immunoglobulin heavy chains. Non-functional ORF generally cannot participate in the synthesis of a productive immunoglobulin chain due to altered V- (D)-J or switch recombination and/or splicing site (at mRNA level) and/or conserved amino acid change (protein level). Immunoglobulins, also known as antibodies, are membrane-bound or secreted glycoproteins produced by B lymphocytes. In the recognition phase of humoral immunity, the membrane-bound immunoglobulins serve as receptors which, upon binding of a specific antigen, trigger the clonal expansion and differentiation of B lymphocytes into immunoglobulins-secreting plasma cells. Secreted immunoglobulins mediate the effector phase of humoral immunity, which results in the elimination of bound antigens. The antigen binding site is formed by the variable domain of one heavy chain, together with that of its associated light chain. Thus, each immunoglobulin has two antigen binding sites with remarkable affinity for a particular antigen. The variable domains are assembled by a process called V-(D)-J rearrangement and can then be subjected to somatic hypermutations which, after exposure to antigen and selection, allow affinity maturation for a particular antigen.
Synonyms: IGHV(III)-51-1; 3-51.1P; IGHVIII-51-1; IGHVIII511
Gene: Immunoglobulin variable (V) gene on chromosome 14 (106,583,501 to 106,583,807, reverse strand). Ensembl gene ENSG00000254167.
Subcellular location: Secreted; Cell membrane
Homologues: Paralogues in human: IGHV3-23 (59% identical), IGHV3-33 (59% identical), IGHV3-43 (59% identical), IGHV3-48 (59% identical), IGHV3-64 (59% identical), IGHV3OR16-10 (59% identical), IGHV3-30 (58% identical), IGHV3-7 (58% identical), IGHV3-74 (58% identical), IGHV3-21 (57% identical), IGHV3-64D (57% identical), IGHV3-13 (56% identical), and 65 more.